MIR152 (microRNA 152)
Synonyms: hsa-mir-152; MIRN152; mir-152
Gene: MicroRNA gene on chromosome 17 (48,037,161 to 48,037,247, reverse strand). Ensembl gene ENSG00000207947.
Gene Ontology:
Biological process: miRNA-mediated post-transcriptional gene silencing
Cellular component: RISC complex
Homologues: Orthologues: pig ssc-mir-152 (97% identical), rabbit MIR152 (94% identical), rat Mir152 (94% identical), chimpanzee MIR152 (89% identical), macaque MIR152 (89% identical), dog MIR152 (83% identical), mouse Mir152 (82% identical), guinea pig MIR152 (79% identical). Paralogues in human: MIR148B (62% identical), MIR148A (57% identical).
Diseases named in the same sentence as MIR152 in open-access papers:
MIR152 is named in the same sentence as 2 diseases in open-access papers, as found by Europe PMC text mining. Sharing a sentence is not in itself a finding about the gene and the disease. The quoted sentences say what the papers report.
cancer (1 paper, 2021). A tumor composed of atypical neoplastic, often pleomorphic cells that invade other tissues. "Pan-cancer analysis showed that MIR129-2, MIR149, MIR152, MIR150, MIR34B, and MIR34C were downregulated in at least four types of cancer, and MIR150 had a protective role against death in most types of cancer." (PMID 33403044, 2021).
MIR152 also shares sentences with these, for which no sentence is quoted: infection (1 paper).